INS (insulin)
Diseases named in the same sentence as INS in open-access papers (continued):
Sharing a sentence is not in itself a finding about the gene and the disease.
metabolic disorders (continued). "Knockdown of TLR4 ameliorates insulin resistances and glucose tolerance, suggesting that TLR4 is a key therapeutic target for metabolic disorders." (PMID 33291425, 2020). "In agreement with the metabolic disorder frequently observed in PCOS, the fasting insulin levels in mice (day 54 of life) with PCOS increased compared with the mice in the vehicle group (P < 0.05)." (PMID 32655632, 2020). "We demonstrated for the first time that shift work could increase insulin sensitivity during the light phase and shift the rhythm of glucose tolerance in female mice, and appropriately adjusting meal times might be an effective method for shift workers to alleviate metabolic disorders." (PMID 31851682, 2019). "When considering correlations between the identified metabolites and classical mediators of metabolic disease such as age, BMI, lipids, FBG, insulin, HOMA-IR and liver function enzymes, a partial correlation analysis revealed several significant associations." (PMID 31640727, 2019). "Since the incapacity of insulin to downregulate PDK4 has been demonstrated in obese and diabetic subjects, the consequent increase in the PDK4 levels associated with an inappropriate suppression of the PDHC activity may promote the development of metabolic diseases." (PMID 29535681, 2018). "Higher insulin levels and HOMA-IR values in the cord blood of preterm newborns support the theory of intrauterine origin of metabolic diseases." (PMID 27087404, 2016). "All these characteristic features of metabolic diseases were prevented by CSN resection meaning that the CB is primordial in controlling peripheral insulin sensitivity and that CB dysfunction is involved in the genesis of these disturbances." (PMID 25400585, 2014). "Our results support the role of NMU in the regulation of insulin production/release, previously observed in experimental studies, and suggest a potential influence of NMU in the development of insulin sensitivity and related metabolic disorders." (PMID 40868161, 2025). "An insulin-centric model recognizes altered insulin biology as not just a marker, but a primary driver of PCOS and its associated reproductive dysfunction and metabolic disease." (PMID 40565766, 2025). "This may be due to the fact that in metabolic disorders, SELENOP inhibits the burst of ROS required for normal insulin signaling due to the powerful reducing effect of SELENOP, so this condition is also known as reductive stress." (PMID 40437610, 2025). "IS drugs may precipitate the onset of metabolic disorders induced by the HFD: tacrolimus has a direct toxicity on the pancreatic Beta cells and decreases insulin secretion." (PMID 40153399, 2025). "Additionally, studies have indicated a reduction in insulin sensitivity and elevated plasma insulin levels during ADT treatment, contributing to a rise in metabolic disorders among those treated." (PMID 40540036, 2025). "The increasing prevalence of this metabolic disorder has driven the development of advanced medical technologies, including smart devices for Continuous Glucose Monitoring (CGM) and insulin infusion sets designated to deliver insulin in a controlled and sustained manner." (PMID 41200730, 2025). "In the state of metabolic disorder induced by a high-fat diet, reactive microglia significantly reduced the inhibitory input of AgRP neurons to β cells by secreting TGF-β, thereby promoting pulsatile insulin secretion." (PMID 41294833, 2025). "However, patients with metabolic diseases showed a decreasing trend in TC, LDL-C, and fasting insulin values." (PMID 38542695, 2024). "However, fasting blood glucose, insulin, and serum alanine aminotransferase levels were higher in males fed an HFD, indicating a more severe metabolic disease." (PMID 39185904, 2024).
metabolic disorders (continued). "Notably, in a recent meta-analysis of 24 RCTs in patients with metabolic diseases, ALA was also found to improve glucose homeostasis (decreased FBG, insulin, HOMA-IR and HbA1c) and lipid profile (decreased triglycerides, total cholesterol and LDL-cholesterol)." (PMID 38952393, 2024). "In terms of metabolic diseases, the most prominent member of the SLC30 family is SLC30A8 (ZnT8), which is located mainly in the insulin-secreting vesicle membrane of β cells in the pancreas and provides the zinc for insulin synthesis." (PMID 39850557, 2024). "We observed physiological changes in serum levels of glucose, insulin and lactate, expected in the population of healthy, young, trained individuals without known metabolic disorder in response to the exercise stimulus (submaximal aerobic exercise)." (PMID 37033257, 2023). "In metabolic disorders, an INI-induced increase in insulin levels and an improvement in the insulin signaling system in the hypothalamus lead to the restoration of mitochondrial functions, an increase in the survival of hypothalamic neurons, and a decrease in oxidative stress and neuroinflammation." (PMID 36834685, 2023). "PAI-1 controls fibrinolysis activity, promoting insulin-resistant conditions such as central obesity, metabolic diseases, non-insulin-dependent diabetes and thrombosis progression." (PMID 36793022, 2023). "Normalization of insulin levels and insulin signaling in the brain, including using INI, may be one of the promising approaches to restore the activity of the gonadal axis in metabolic disorders." (PMID 36834685, 2023). "Furthermore, the abundances of these miRNAs correlated with biomarkers of metabolic disease, which includes circulatory C-peptide, HOMA2-IR, plasma insulin and HbA1c." (PMID 37762694, 2023). "Microbiota transplantation improves glucose homeostasis and insulin sensitivity in HFD-induced obese mice, which highlights the metabolic benefits obtained by habitual exercise and FMT application in the management of metabolic disease." (PMID 36915683, 2023). "Overall, the immediate metabolic effects of exercise are mostly independent of insulin, but exercise training can increase insulin sensitivity in the muscles, making it a valuable tool for preventing and treating metabolic diseases." (PMID 37445852, 2023). "We and others have previously shown that insulin reduces AIx75 and AP during euglycemia in adults with MetS and without metabolic disease." (PMID 36301720, 2022). "Researchers have reported that drug-naïve patients or patients from the pre-medication era have metabolic disorders such as a higher body mass index (BMI), waist circumference, and low-density lipoprotein (LDL) levels; hyperinsulinemia; and abnormalities in insulin secretion." (PMID 36188456, 2022). "Allobaculum could improve insulin sensitivity, increase the level of gut short-chain fatty acids (SCFA) and reduce systemic inflammation, and consequently prevent the occurrence of metabolic diseases." (PMID 35334934, 2022). "DM describes metabolic diseases that lead to elevated blood glucose levels due to a lack of insulin or a reduced effectiveness of insulin." (PMID 35846001, 2022). "Most DEGs were related to substances related to metabolic diseases, such as thyroid hormone synthesis, the AMPK signaling pathway, the glucagon signaling pathway, insulin secretion, fatty acid biosynthesis, cortisol synthesis and secretion and vasopressin-regulated water reabsorption." (PMID 35954098, 2022). "Type 2 diabetes (T2D) is a chronic and life-changing metabolic disorder that occurs when the pancreas does not produce enough insulin, or the body cannot effectively use the insulin it produces to regulate blood sugar." (PMID 36297075, 2022). "The negative correlation between ING fat mass and insulin sensitivity was somewhat unexpected as the ability to expand subcutaneous fat in humans has been suggested to be protective against metabolic diseases." (PMID 36158197, 2022).
metabolic disorders (continued). "Further, we have determined that glucocorticoid exposure during this window of development results in dysregulation of insulin and IGF1 signaling and an adaptive immune response in the TE, suggesting the potential development of altered placental capacity and metabolic disease later in life." (PMID 35948369, 2022). "The absence of insulin leads to metabolic disorders and glucose metabolic barrier, and patients with T2DM presented a high glucose level." (PMID 35419355, 2022). "Compared with the control group, PCOS patients had significantly increased levels of LH, total testosterone, androstenedione, AMH, fasting insulin, TG, T-CHO and LDL-C, which were in accordance with the typical abnormal characteristics of endocrine and metabolic disorders in PCOS." (PMID 35721725, 2022). "Whole-body insulin sensitivity decreases throughout the day, which is why it seems that food intake at the beginning of the day is preferable, making early TRF the chosen method for improving and preventing metabolic diseases." (PMID 33808424, 2021). "Insulin administration is high among CABG patients and could reverse most of these metabolic disorders." (PMID 34236791, 2021). "Hypertrophic adipocytes and an impaired redistribution of lipids exert a negative impact on insulin responsiveness, contributing to many metabolic diseases frequently observed in the elderly." (PMID 33904399, 2021). "Finally, to further link to metabolic diseases which commonly involve poor blood glucose management, we will review how TMAO affects insulin resistance and insulin secretion." (PMID 34445033, 2021). "T1DM and T2DM are metabolic disorders in which insulin secretion is reduced (T2DM) or no longer secreted due to pancreatic-cell death (T1DM)." (PMID 34827690, 2021). "Studies have found that the anti-lipolytic effect of insulin can be adjusted through the AKT/PKA/HSL signaling pathway, and inhibiting excessive lipolysis of adipose tissue is an important way to treat metabolic diseases." (PMID 34366839, 2021). "Further study showed that the interaction between postbiotics (like muropeptide) and NOD2 could improve insulin sensitization and inflammation, but the connection with NOD1 could worsen metabolic disorders." (PMID 34579087, 2021). "Several prior studies have provided evidence that having little or no adipose tissue leads to metabolic disease; mouse models with congenital deficiencies of WAT are almost unequivocally insulin-resistant." (PMID 33732506, 2021). "In the present study, we observed that FO and PO had similar adjusting roles on body weight, glucose, insulin, TG, TC, IL-6, and adipocyte counts in C57BL/6J mice fed a HF diet, indicating comparable regulations in metabolic disorders and inflammation between marine and plant ω−3 PUFA." (PMID 34168108, 2021). "Overall, improving our understanding of how and when physiological H2O2 is involved in the regulation of insulin signalling under healthy conditions, and how H2O2 contributes to the progression of metabolic diseases will improve prospects for successful therapeutic interventions." (PMID 33893069, 2021). "Insulin signaling and AGE-RAGE signaling pathway in diabetic complications (among 27 immune-relevant pathways) were identified based on DEGs in sick vs. healthy fish, suggesting a disease-induced endocrine and metabolic disorder." (PMID 34220943, 2021). "Another in vivo study revealed that diet supplementation with butyrate mitigated metabolic disorder and intestinal epithelial impairment in type 2 diabetic mice by promoting the secretion of insulin without compensatory hyperplasia in pancreatic β cells." (PMID 34579087, 2021). "However, compared with healthy patients receiving insulin stimulation, the expression of mTOR protein in the corpus luteum of PCOS patients is less, so another link between PCOS and mTOR is metabolic disorders during PCOS." (PMID 32785222, 2020).
metabolic disorders (continued). "It did not investigate the direct effect of metabolic disorders and IR on circulating Fetuin-B, nor did it dynamically observe the changes of circulating Fetuin-B levels with the increase of insulin sensitivity." (PMID 33061822, 2020). "Delicately, there was a meta-analysis reported that fish oil had a positive effect on insulin sensitivity in people with metabolic disorders rather than healthy individuals and patients with clinically overt T2DM groups." (PMID 32384902, 2020). "We also explored whether blood from WT mice affects the metabolic disorders in Tie2-TERF2DN-Tg mice, and found that shared circulation with WT mice partly reversed the impaired insulin sensitivity in Tie2-TERF2DN-Tg mice." (PMID 31980643, 2020). "It is a severe metabolic disease that occurs in two types: type I, so-called insulin-dependent, and type II, non-insulin-dependent." (PMID 32102185, 2020). "DM is a metabolic disease related either to the failure to generate insulin for proper utilization of glucose (type 1) or insulin resistance when the produced hormone is not able to interact with its receptors (type 2)." (PMID 32350344, 2020). "NobiletinNOB effectively reversed glucolipid metabolism disorders triggered by PA by increasing the insulin/IGF-1 signaling pathway and regulating key enzymes of de novo lipogenesis." (PMID 31408938, 2019). "On administering standard laboratory chow, no metabolic disorder was detected, except for a difference in insulin sensitivity." (PMID 30679431, 2019). "Our data suggest that the insulin/Snail1/epigenetic axis may serve as a potential therapeutic target for the treatment of NAFLD and metabolic disease." (PMID 30013137, 2018). "Although we investigated factors which are major indicators of metabolic health, prepregnancy adiposity and third trimester insulin response do not fully represent the complexity of metabolic disorders." (PMID 29740395, 2018). "Thus, identifying the molecular basis of improving insulin sensitivity is a plausible therapeutic approach for T2DM and related metabolic diseases." (PMID 30347867, 2018). "Thermogenic, weight reducing and insulin sensitizing effects of phosphodiesterase 5 (PDE 5) inhibitors have recently been postulated, suggesting that modulators of endogenous cGMP signaling have the therapeutic potential to treat metabolic disorders." (PMID 29549244, 2018). "DM is a metabolic disorder characterized byhyperglycemia in the context of insulin resistance and relative lack of insulin.Both diseases also share common characteristics such as loss of cognitivefunction and inflammation." (PMID 29213501, 2017). "In contrast, each additional daily hour spent sedentary was cross-sectional associated with a 3% higher fasting insulin and HOMA-IR, but did not predict 5-year changes in metabolic parameters or incidence of metabolic disorders." (PMID 28503154, 2017). "Type 2 diabetes, which is also called noninsulin-dependent diabetes mellitus (NIDDM) or adult-onset diabetes, is a metabolic disorder that is characterized by high blood sugar in the context of insulin resistance and relative lack of insulin." (PMID 26818594, 2016). "Thus, while there is some evidence that replacing high-GI foods with low-GI foods may help decrease the risk of metabolic disease, it has not been possible until now to quantify the extent to which the low glycaemic response associated with a lower insulin response is beneficial." (PMID 27388153, 2016). "Thus, metabolic disorders can potentially be treated by inducing GPR119 activation and stimulating both GLP-1 and insulin secretion." (PMID 27023530, 2016). "Due to the limitation of sample size and exclusion of subjects with metabolic disorders in the current study, we did not observe any differences in the levels of plasma glucose, insulin, or HOMA-IR." (PMID 25120532, 2014).
metabolic disorders (continued). "Ultimately, a better understanding of the crosstalk involved in insulin signaling may lead to improved therapeutic and prevention strategies of ALMS and other metabolic diseases involving IR." (PMID 25299671, 2014). "If these data are confirmed in long‐term studies, it would imply that the use of leucine/HPD in treating metabolic diseases is unlikely to have lasting negative effects on insulin sensitivity." (PMID 24997070, 2014). "In this study, we excluded subjects with metabolic disorders, thus, the levels of glucose, insulin, and C-peptide were not different between tasters and non-tasters." (PMID 25120532, 2014). "TFL has a beneficial effect on metabolic disorder in relation to improved circulating insulin levels without affecting hepatic lipid metabolism-related gene expressions in rats." (PMID 23476149, 2013). "TFL has a beneficial effect for metabolic disorder in relation to improved circulating insulin levels without affecting hepatic lipid metabolism-related gene expressions in rats." (PMID 23476149, 2013). "The fact that no previous studies have investigated the role of miRNAs in insulin signaling accounts for the lack of research into their potential as therapeutic targets for metabolic disease." (PMID 21464990, 2011). "In the context of metabolic disease, sustained oxidative distress has been shown to impair GLUT4 translocation and dysregulate downstream effectors, highlighting the dual role of ROS as both facilitators and inhibitors of insulin action depending on concentration, duration, and cellular context." (PMID 41226411, 2025). "In this work, insulin rescue experiments combined with mosquito brain immunostaining have revealed that the metabolic disorder observed in iE93 mosquitoes was primarily caused by insufficient ILP3 production in mosquito brains, rather than alterations in insulin sensitivity." (PMID 41160608, 2025). "Taken together, the in vivo evidence suggests that CREBZF is required for the beneficial effects of bromocriptine on anti‐inflammatory phenotype and improved insulin sensitivity in mice, and pharmacological inhibition of CREBZF may have potential therapeutic effects on metabolic disorders." (PMID 38286660, 2024). "could induce AD-like metabolic disorders and behavioral impairments in mice, including increased blood glucose levels and serum insulin levels and and impaired cognitive ability in NOR, Y-maze, and MWM tests." (PMID 39626951, 2024). "Besides, deletion of IP6K1 increases insulin sensitivity, and alleviates hepatic metabolic dysfunction, indicating that IP6K1 may be a potential treatment target for metabolic diseases." (PMID 39643078, 2024). "Furthermore, several investigations have shown that the absence of the α7 subunit of nAChRs leads to metabolic disorders in mice and affects insulin release and response." (PMID 38731463, 2024). "Bridging knowledge gaps between mammalian and non-mammalian INS signaling has the potential to expand our comprehension of evolutionary biology, provide novel insights into metabolic disease pathophysiology, and afford valuable knowledge for the conservation of coral species." (PMID 38313028, 2024). "could induce not only T2DM-like metabolic disorders but also AD-like neuropsychiatric behavior in mice, as indicated by the increased blood glucose levels and serum insulin levels and the impaired cognitive ability in NOR, Y-maze, and MWM tests." (PMID 39626951, 2024). "Furthermore, the activity of the branched-chain α-ketoacid dehydrogenase complex is shown to be reduced in conditions of impaired insulin function, reducing catabolism of BCAA reflected by the characteristic elevation of their circulating levels in individuals with metabolic disease." (PMID 39687851, 2024). "Importantly, there are no reports of the possibility to condition insulin responses in metabolic disorders." (PMID 37234022, 2023).